IRF1 (interferon regulatory factor 1)
Diseases named in the same sentence as IRF1 in open-access papers (continued):
Sharing a sentence is not in itself a finding about the gene and the disease.
celiac disease (4 papers, 2017 to 2023). An autoimmune genetic disorder with an unknown pattern of inheritance that primarily affects the digestive tract. "Most interestingly, IRF1 was also upregulated by celiac disease-associated bacteria." (PMID 28934294, 2017). "IRF1 is reported also to be highly expressed in celiac disease and being important for robust TH1-macrophage responses." (PMID 36282455, 2023). "Dual activation of IRF1 and IRF1-regulated genes, both directly and via the interleukin-18 dependent inflammasome would drastically enhance the inflammatory response and lead to the pathological situation seen in active celiac disease." (PMID 28934294, 2017). "IRF1 plays a role in triggering gluten intolerance that itself is being suppressed by STAT1." (PMID 29379596, 2017). "A key factor in the epithelial reaction in celiac disease appears to be over-expression of IRF1 that could be inherent and/or due to presence of undesirable microbes that act directly on IRF1." (PMID 28934294, 2017).
chronic kidney disease (4 papers, 2019 to 2025). Impairment of the renal function secondary to chronic kidney damage persisting for three or more months. "Patients with chronic kidney disease and histological evidence of fibrotic processes in their kidneys displayed elevated levels of IRF1." (PMID 37508555, 2023). "However, the data on the relationship between IRF1 or IRF4 and chronic kidney disease mainly come from murine studies, and conclusions on the clinical significance of IRF1 and IRF4 for chronic kidney disease should be elucidated in future studies." (PMID 37508555, 2023). "The initial increase in upregulation of IRF1 expression, coinciding with the initial mild kidney chronic disease, might be considered a prognostic factor of renal scarcity." (PMID 31507612, 2019).
colon adenocarcinoma (4 papers, 2020 to 2025). "In colon adenocarcinoma, IRF1 correlated with metastasis and the extent of immune cell infiltration, including CD8+ T cells, dendritic cells, T-helper 1 cells, and T cell exhaustion." (PMID 39941858, 2025).
depression (4 papers, 2020 to 2025). "However, we could hypothesize that stress causes increased IRF1 expression and thus increased activation of inflammatory pathways, which is commonly observed in the course of depression." (PMID 33946816, 2021). "Nevertheless, our findings confirm at least a partial association between TGFA, TGFB, PTGS2, IRF1 and IKBKB genes and depression, and hence it is highly likely that inflammation plays a role in psychiatric disorders." (PMID 33946816, 2021). "Summarizing, our results confirm at least a partial association between TGFA, TGFB, IRF1, PTGS2 and IKBKB and depressive disorders." (PMID 33946816, 2021). "Gene-gene interactions of rs1800469 (TGFB1), rs2070729 (IRF1), rs5275 (PTGS2), rs4648308 (PTGS2), rs2166975 (TGFA), rs5029748 (IKBKB) and the risk of depression occurrence." (PMID 32140313, 2020). "We observed that A/G of the rs2166975 TGFA, A/C of rs2070729 IRF1 and G/T of rs5029748 IKBKB were associated with an increased risk of depression development while the T/T of rs5029748 IKBKB, T/T of rs4648308 PTGS2 and G/G of rs2166975 TGFA reduced this risk." (PMID 32140313, 2020). "Distribution of genotypes and alleles of rs2070729 (IRF1), rs5275 (PTGS2), rs4648308 (PTGS2), rs2166975 (TGFA), rs5029748 (IKBKB) and the risk of depression occurrence in male and female population." (PMID 32140313, 2020). "Distribution of genotypes and alleles of rs1800469 (TGFB1), rs2070729 (IRF1), rs5275 (PTGS2), rs4648308 (PTGS2), rs2166975 (TGFA), rs5029748 (IKBKB) and the risk of depression occurrence." (PMID 32140313, 2020). "Concluding, our results indicate that TGFA, TGFB, PTGS2, IRF1 and IKBKB could be associated with depression and its treatment." (PMID 36012250, 2022). "Through comprehensive molecular regulatory network analysis, transcription factors such as ATF1, IRF1, HBP1, DRAP1, TGIF2, and TFDP1 were identified as potential regulatory factors in depression, warranting further exploration." (PMID 40370590, 2025). "This study focuses on the contribution of genes such as IRF1, PTGS2, IKBKB, TGFA and TGFB in the molecular basis of depression as well as the impact of chronic agomelatine administration." (PMID 36012250, 2022). "The present study is the first to investigate the levels of TGFA, IRF1 and IKBKB mRNAs in an animal model of depression." (PMID 33946816, 2021). "Our key findings reveal that TGFA, TGFB, PTGS2, IRF1 and IKBKB could be responsible for immune system activation in depression." (PMID 36012250, 2022). "To date, there has been no research regarding the role of IRF1 in depression and other psychiatric disorders, nor the level of its expression in these conditions." (PMID 33946816, 2021). "In this research, we genotyped six polymorphic variants of TGFA, TGFB1, IRF1 and PTGS2 genes; and to our knowledge, none of this SNPs have been studied in the context of severity and treatment response in depression before." (PMID 32140313, 2020).
diabetic kidney disease (4 papers, 2020 to 2023). Progressive kidney disorder caused by vascular damage to the glomerular capillaries, in patients with diabetes mellitus. "Yet, there is still limited report on the association between other 5 transcription factor genes (CDC5, FAC1, HFH1, IRF1 and TGIF1) and diabetic nephropathy." (PMID 36978091, 2023).
diffuse large B-cell lymphoma (4 papers, 2019 to 2025). "Immune responses in diffuse large B-cell lymphoma are related to the IFN-γ-STAT1- Interferon regulatory factor 1 axis." (PMID 31671580, 2019).
endotoxemia (4 papers, 2015 to 2020). "HDAC6 regulates LPS-induced iNOS expression in macrophages by modulating STAT1 activation and IRF-1 expression, and facilitates iNOS expression in the tissues during endotoxemia." (PMID 32973784, 2020). "The capacity for IRF-1 to promote apoptosis and inhibit autophagy in splenocytes was demonstrated within endotoxemia, and a relationship between IRF-1 and autophagy was also reported in tumor cells." (PMID 27191889, 2016). "Here, we demonstrate that IRF1 acts as a critical modulator in transforming macrophages into lipid-laden foam cells, and provide novel evidence explaining the link between subclinical endotoxemia and foam cell transformation." (PMID 31367250, 2019). "However, another recent study demonstrated increased autophagy and decreased apoptosis in IRF1 knockout mice in a murine endotoxemia model." (PMID 26362401, 2015). "Interestingly, theses effects were nearly ablated in macrophages from IRF1-/- mice, indicating that IRF1 might play an important role in mediating the pro-atherosclerotic effects of endotoxemia." (PMID 31367250, 2019).
Hepatitis (4 papers, 2017 to 2024). Inflammation of the liver. "Constitutive IRF1 activity has been implicated in intrinsic IIR hepatitis A infection in hepatocytes." (PMID 38601157, 2024). "In the present study, we found that IRF-1 expression was up-regulated in response to hepatic IR and accompanied by a corresponding activation of autophagy via P38/P62 activation." (PMID 28266555, 2017).
liver diseases (4 papers, 2024 to 2025). "IRF1, a nuclear transcription factor, was involved in various liver diseases, particularly hepatic IRI and HCC." (PMID 38999981, 2024). "In addition to IRF1, other members of the IRF family have also been discovered to play significant roles in various liver diseases, demonstrating diverse functions in either promoting or inhibiting these diseases." (PMID 38999981, 2024).
lymphoma (4 papers, 2011 to 2021). A malignant (clonal) proliferation of B- lymphocytes or T- lymphocytes which involves the lymph nodes, bone marrow and/or extranodal sites. "Irf-1_/_/CN2 mice showed extremely high incidences of lymphomas and lymphoproliferative disorders." (PMID 22084693, 2011). "Several other genes are members of the family of known lymphoma drivers, such as CXCR5, HIST2H3D, ID2 and IRF1." (PMID 33945543, 2021). "A significant percentage of the mice that expressed the HCV core protein (irf-1−/− CN2 mice) showed polyclonal lymphoid growth disturbances, including splenomegaly, expanded lymph nodes, adenocarcinoma in the abdomen or leg, and lymphoma of the liver or Peyer's patches." (PMID 22084693, 2011).
myelodysplastic syndrome (4 papers, 2011 to 2025). A clonal hematopoietic disorder characterized by dysplasia and ineffective hematopoiesis in one or more of the hematopoietic cell lines. "A study of bone marrow and peripheral blood samples from patients with myelodysplastic syndrome and chronic myelocytic leukemia identified IRF1 variants lacking exon 2 or both exons 2 and 3 (IRF1Δ2 and IRF1Δ23)." (PMID 38396830, 2024).
myeloma (4 papers, 2015 to 2023). "We also demonstrate that myeloma cells upregulate the expression of CIITA in osteocytes through TP/2DDR-mediated STAT1/IRF1 signaling." (PMID 35760800, 2022). "We found a similar pattern for IRF1 in monocytes from a single-cell RNA sequencing study examining patients with myeloma." (PMID 34847931, 2021). "Roughly 33% IRF1/BLIMP1 overlap was predicted in human myeloma cells, whereas here Irf1 and Blimp1 ChIP-seq peaks show approximately 12% (n = 331) overlap." (PMID 26158850, 2015). "In turn, myeloma cell–secreted 2-deoxy-D-ribose, the product of thymidine catalyzed by the function of thymidine phosphorylase, upregulates CIITA expression in osteocytes through the STAT1/IRF1 signaling pathway." (PMID 35760800, 2022).
osteoarthritis (4 papers, 2013 to 2025). A noninflammatory degenerative joint disease occurring chiefly in older persons, characterized by degeneration of the articular cartilage, hypertrophy of bone at the margins and changes in the synovial membrane. "In osteoarthritis, GBP5 expression is significantly upregulated in TNF‐α‐treated chondrocytes, where IRF1 promotes GBP5 transcription, triggering NLRP3 inflammasome activation and promoting pyroptosis." (PMID 40636987, 2025).
parasite infection (4 papers, 2011 to 2023). "Despite these findings, parasite infection blocked STAT1 binding to the native promoters of the IFNγ-inducible genes Irf-1 and Lrg47, along with subsequent gene expression." (PMID 23527309, 2013). "However, more recent findings have also identified PLAAT4 as a key anti-microbial effector enzyme acting downstream of interferon regulatory factor 1 (IRF1) and interferons (IFNs), favoring protection from virus and parasite infections." (PMID 37063830, 2023). "Moreover, IRF-1-/- Mφ have decreased IL-12 production during bacterial and parasitic infection, whereas IRF-1-/- CD4+ T cells show reduced IL-12 receptor expression and are prone to TH2 skewing." (PMID 21909274, 2011). "Moreover, IRF-1-/- mice also have defects in TH1 responses due to altered production of IL-12 by Mφ and hypo-responsiveness of T cells to the effects of IL-12 during bacterial and parasite infections." (PMID 21909274, 2011).
pulmonary TB (4 papers, 2013 to 2023). "Furthermore, inactivating mutations in several of these common genes including Irf8, Irf1, and Irgm1 cause susceptibility to pulmonary tuberculosis, while conveying some degree of protection against ECM." (PMID 23853600, 2013). "According to the results of GSEA, most of the genes in the tissue samples of the high expression IRF1 group were enriched in the temperature regulation functional area, indicating that there was a higher inflammatory response in the focus of pulmonary tuberculosis." (PMID 34213077, 2021). "Our study identified unique gene signatures (IL-27, STAT1, IRF1, TLR4, IL-15, IL-2RA, IL-24, TGFβ, CD28, CD80, NFATC1, and PTGDR2) that discriminate active pulmonary TB from uninfected controls using unstimulated PBMCs." (PMID 37460564, 2023). "In active pulmonary TB patients with high bacterial burden, miR-23a-3p expression was decreased, affecting the balance between TLR4 and IL10 immunologic responses by down-regulating SP1/IRF1 expression and further influencing TLR4/IL10 expression ratio." (PMID 33202583, 2020).
renal carcinoma (4 papers, 2016 to 2025). A carcinoma arising from the epithelium of the renal parenchyma or the renal pelvis. "In human Ketr-3 and 786-O renal carcinoma cells, IRF1 was found to repress Ki-67 gene transcription in a dose-dependent manner." (PMID 27191889, 2016).
rosacea (4 papers, 2021 to 2025). A chronic erythematous skin disorder that affects the face. "Our findings showed a significant positive association with increased expression of IRF1 in the blood (OR = 5.21, p = 2.71E‐08) and an elevated risk of rosacea; the strong evidence of colocalization suggested a potential role in the pathogenesis of the disease (PP.H4 = 0.973)." (PMID 40635520, 2025). "Through the comprehensive analysis of rosacea of three tissues, SMR analysis identified three druggable genes in human blood that were causally associated with rosacea‐related traits (p‐FDR < 0.05), including P4HA2, IRF1, and SLC22A5." (PMID 40635520, 2025). "In summary, we confirmed the causal relationship between IRF1 and SLC22A5 and the risk of rosacea using MR and Bayesian colocalization analysis." (PMID 40635520, 2025). "In this research, we identified an important causal relationship between two druggable genes, IRF1 and SLC22A5, and the development of rosacea." (PMID 40635520, 2025). "We further identified common inflammatory signatures, the TF network in whole-skin and epidermis, and epidermal STAT1/IRF1 signature and epithelial–immune crosstalk for rosacea lesions." (PMID 34290700, 2021). "By immunohistochemistry we also demonstrated that the nuclear localization of phosphor-STAT1 and IRF1 was increased in epidermal cells of rosacea lesions." (PMID 34290700, 2021). "Upregulated expression of IRF1 in patients with rosacea was confirmed by GEO data sets." (PMID 40635520, 2025). "Although direct evidence of the IRF1 pathway in rosacea requires further validation, this finding suggests that environmental factors (UV exposure) may exacerbate disease progression through IRF1‐dependent mechanisms." (PMID 40635520, 2025). "Second, due to the lack of genetic studies at the protein level, we were unable to confirm whether the protein quantitative trait loci for IRF1 and SLC22A5 were associated with the risk of rosacea." (PMID 40635520, 2025). "There is an overactive keratinocyte–macrophage crosstalk via the epidermal-derived IFN-γ/STAT1/IRF1 signature in rosacea, which might be an argument for the activation of the innate immune system for rosacea development." (PMID 36091020, 2022). "Furthermore, STAT1 and IRF1 were identified across all rosacea subtypes." (PMID 34290700, 2021). "GEO data sets confirmed significant upregulation of IRF1 and downregulation of SLC22A5 in rosacea patients." (PMID 40635520, 2025). "This study identified IRF1 and SLC22A5 as potential drug targets for the treatment of rosacea, and their significant therapeutic potential provides a critical foundation for the development of targeted therapies." (PMID 40635520, 2025). "MR and SMR analyses identified IRF1 and SLC22A5 as druggable genes for rosacea, with Bayesian colocalization strongly supporting shared causal variants." (PMID 40635520, 2025). "By analyzing the GSE65914 data sets, we evaluated the expression of IRF1 and SLC22A5 genes in the three major subtypes of rosacea." (PMID 40635520, 2025). "The expression of CXCL10, MMP9, IL1B, CXCL8, and CXCR4 were co-regulated by IRF1, STAT1, STAT3, IKBKB, HDAC1, ETS1, and CEBPB, which were highly expressed in rosacea and acne lesions." (PMID 38321132, 2024). "Further verification of the GSE65914 and GSE125733 datasets was performed, and STAT1, which is involved in the regulation of three hub genes (IRF1, IRF8, and CXCL10), was found to be differentially expressed in FFA and rosacea." (PMID 36091020, 2022). "Consistently, by immunohistochemistry we verified the increased nuclear localization of phosphor-STAT1, IRF1 and IRF8 in both epidermis and dermal infiltration of rosacea lesions." (PMID 34290700, 2021). "Finally, although our MR Analysis identified IRF1 and SLC22A5 as potential drug targets for rosacea, these findings remain hypothetical at this time and require further validation in experimental models." (PMID 40635520, 2025).
rosacea (continued). "HEIDI tests showed that the association between expression levels of IRF1, SLC22A5, and rosacea was not caused by linkage imbalance (p > 0.01)." (PMID 40635520, 2025). "IRF1 regulated the IFNγ/STAT1 signaling pathway in keratinocytes and enhanced their interaction with macrophages, which drove the persistent inflammatory response of rosacea and then induced clinical manifestations such as pustules, papules, and heat pain." (PMID 40635520, 2025). "In addition, we identified the critical role of IRF1 and IRF8 in FFA and rosacea and the high expression of STAT1 in this study." (PMID 36091020, 2022). "Our findings provide a new model that diverse inflammatory processes in rosacea may be driven largely by just a small number of hubs within the epidermal transcription circuitry, such as STAT1/IRF1." (PMID 34290700, 2021). "Furthermore, in terms of the effect of STAT1/IRF1 on M1 polarization, our previous study found that ADAMDEC1 plays a pro-inflammatory role in rosacea by modulating the M1 polarization of macrophages." (PMID 34290700, 2021). "Therefore, the IFN-γ/STAT1/IRF1 pathway might regulate M1 polarization in the presence of FFA and rosacea." (PMID 36091020, 2022).
testicular embryonal carcinoma (4 papers, 2011 to 2017). A malignant germ cell neoplasm arising from the testis. "miR-383 is associated with male infertility and promotes testicular embryonal carcinoma cell proliferation by acting as a negative regulator of proliferation by targeting IRF-1 (Interferon regulatory factor 1)." (PMID 23826142, 2013). "A previous report has shown that in testicular embryonic carcinoma cells miR-383 induces a decreased proliferation rate by targeting interferon regulatory factor-1 (IRF1), implying that miR-383 exerts effects through various targets." (PMID 25415264, 2014). "Both IRF1 protein and IRF1 mRNA expressions were significantly decreased in miR-383-transfected NT2 (testicular embryonal carcinoma) cells." (PMID 29186904, 2017).
ulcerative colitis (4 papers, 2019 to 2025). An inflammatory bowel disease involving the mucosal surface of the large intestine and rectum. "In keeping with these findings, our lead SNP rs2070721-G was associated with reductions in IRF1 expression and ER-positive breast cancer risk and increased autoimmune/autoinflammatory disease (ulcerative colitis) risk." (PMID 40428397, 2025). "While IRF1 is a plausible candidate as a key immune regulator with links to many ulcerative colitis-related genes, functional data implicating IRF1 has been thus far lacking." (PMID 34314424, 2021).
allergic disease (3 papers, 2012 to 2025). An immune response that occurs following re-exposure to an innocuous antigen, and that requires the presence of existing antibodies against that antigen. "The influence of a child's genotype on the development of immune-mediated diseases such as allergic diseases has been shown in several studies, e.g. for IRF1 or TLR polymorphisms." (PMID 22303482, 2012).